LATS1 (large tumor suppressor kinase 1)
Diseases named in the same sentence as LATS1 in open-access papers (continued):
Sharing a sentence is not in itself a finding about the gene and the disease.
melanoma (continued). "RASSF1A, a tumour suppressor repressed by promoter methylation in more than 50% of advanced melanomas, stimulates LATS1-dependent apoptosis both through the intrinsic and extrinsic apoptotic pathways." (PMID 35941108, 2022). "The second affinity purification-mass spectrometry (AP-MS) screen was performed in A375 cells to understand how SMAC levels regulate LATS1 interactome in melanoma cells." (PMID 35941108, 2022). "In BRAFi resistant melanoma cells developed in our group, we show that LATS1 and MST2 expression is reduced because of ubiquitin ligase-dependent degradation." (PMID 36038253, 2022). "To this end, we treated proliferative M000921 and M010817 patient-derived melanoma cells with either recombinant human TGFβ or with recombinant murine Wnt-3a, or we knocked down LATS1 and LATS2 to induce the transcriptional activity of YAP/TAZ." (PMID 34819356, 2022). "Altogether, these experiments clearly showed that the core proteins of the proapoptotic MST2 pathway regulate LATS1-SMAC interaction in melanoma cells." (PMID 35941108, 2022). "RASSF1A expression is commonly lost in melanoma patients, and the expression of LATS1 is often down-regulated." (PMID 36038253, 2022). "The study demonstrated that LATS1 is highly engaged in melanogenesis and oxidative stress control and affects melanoma growth." (PMID 33803640, 2021). "The major finding of our study is that LATS1 silencing leads to a significant decrease in the expression of melanogenesis driver genes and melanin content, both in primary melanocytes and melanoma cells." (PMID 33803640, 2021). "We have knocked down LATS1 in primary melanocytes and melanoma cells and found that its expression is crucial for melanin synthesis, ROS production, and oxidative stress response." (PMID 33803640, 2021). "To address the importance of LATS1 in melanin biosynthesis, we knocked down LATS1 gene in highly pigmented primary human adult epidermal melanocytes (HEMa) as well as in MeWo melanoma cell line." (PMID 33803640, 2021). "In our model HIF1 expression is stable in melanoma cell line and rises after LATS1 knockdown, but increases in modified melanocytes." (PMID 33803640, 2021). "Following the demonstration that LATS1 is crucial for melanogenesis, its effects on other functions of melanocytes and melanoma cells were analyzed." (PMID 33803640, 2021). "We also indicate the critical role of LATS1 in melanoma growth since both processes affect tumor formation." (PMID 33803640, 2021). "We observed highly elevated AOX1 gene expression in LATS1 knocked down cells, both in melanocytes and melanoma cell line." (PMID 33803640, 2021). "We showed that LATS1 ablation significantly decreased the melanogenesis markers’ expression and melanin synthesis in melanocyte and melanoma cell lines." (PMID 33803640, 2021). "Further research needs to be carried out to characterize other elements of the Hippo pathway in melanoma, particularly upstream elements such as Lats1/2." (PMID 23720711, 2013). "To verify whether ACSS2’s pro-oncogenic effects in melanoma were mediated via the Hippo pathway, we employed GA-017, a LATS1/2 inhibitor, to deactivate this pathway." (PMID 38887280, 2024). "Thus, we overexpressed LATS1 in the amyloid-deficient melanoma cells IGR39, we administered recombinant PMEL and we checked the level of LATS1 and p-YAP (Ser127), a marker of YAP cytosolic retention." (PMID 38199984, 2024). "Moreover, studies observed co-heterozygous loss of LATS1/2 and amplification of YAP1 in primary and metastatic human melanoma." (PMID 38515849, 2024). "In addition to highlighting the role of LATS1/2 kinases in melanoma development, that study also pointed to YAP/TAZ as promising therapeutic targets, as constitutively active YAP caused extended tumor formation in zebrafish." (PMID 38920690, 2024).
melanoma (continued). "Since RASSF1A expression is lost in these cell lines, we postulated that the lack of expression of RASSF1A could impair LATS1 proapoptotic signalling in melanoma, explaining the resistance to LATS1 overexpression observed in these cell lines." (PMID 35941108, 2022). "In support of this hypothesis, both BrafV600E/Lats1/2−/− and Lats1/2−/− mouse melanomas exhibited markedly low staining for mature, differentiated melanocyte markers." (PMID 35768444, 2022). "However, sequencing revealed that all tumors from these models were diploid, excluding the possibility that Lats1/2 deletion was primarily inducing melanoma through a WGD intermediate." (PMID 35768444, 2022). "Indeed, elevation of MST2 and LATS1 protein concentrations induced apoptosis in PLX4032 resistant melanoma cells." (PMID 36038253, 2022). "Since WGD is well known to facilitate tumorigenesis, and a significant fraction of human melanomas are WGD, we speculated that Lats1/2 loss may drive tumorigenesis in vivo through an initial WGD event." (PMID 35768444, 2022). "We have also shown that LATS1 is degraded by induction of ubiquitination in melanoma cells." (PMID 35941108, 2022). "As a first step, LATS1 was overexpressed in three different melanoma cell lines." (PMID 35941108, 2022). "We observed that melanomas generated from Lats1/2−/− mice exhibited strong p-ERK staining." (PMID 35768444, 2022). "Finally, we show that the restoration of LATS1 proapoptotic signalling in combination with SMs can restore the sensitivity of melanoma cells to apoptosis." (PMID 35941108, 2022). "Our data so far shows that IAP protein levels could determine melanoma cells sensitivity to LATS1-induced apoptosis." (PMID 35941108, 2022). "We aimed to further define how deletion of Lats1/2 promotes melanoma development in vivo." (PMID 35768444, 2022). "Moreover, knocking down LATS1 increased hypoxia state and oxidative stress inside the melanocytes and melanoma cells." (PMID 33803640, 2021). "Such an effect might be related to the decreased expression of several CSC genes such as Lats1, Stat3, and Foxp1 in the ALDHhigh cells (data not shown) reported to be associated with melanoma aggressiveness." (PMID 35408953, 2022). "Further, the loss of upstream regulators of the Hippo-YAP pathway, such as SAV1 and LATS1, leads to uncontrolled YAP activation and cancer cell growth in melanoma." (PMID 41550920, 2025). "A study indicates that triptolide can inhibits aggressive melanoma cell growth and metastasis by inducing SAV1 and LATS1 expression and activation of the Hippo pathway." (PMID 38887280, 2024). "Our previous results suggested that RASSF1A was regulating LATS1-SMAC interaction, and that RASSF1A regulates LATS1 signalling in melanoma." (PMID 35941108, 2022). "Treatment of resistant melanoma cells with proteasome inhibitors rescues MST2 and LATS1 expression and restores proapoptotic signalling." (PMID 36038253, 2022). "Recent reports show that YAP signaling may support immune evasion in cancer and melanoma by inducing PD-L1 expression, whereas others show that enhanced YAP signaling, due to loss of the regulating kinases large tumor suppressor kinase 1 and 2 (LATS1/2), may promote an anti-cancer immune response." (PMID 32332858, 2020). "These LATS1/2-null tumor cells induced type I interferon production by releasing EVs and activating the TLRs-MYD88/TRIF pathway, thereby potentiating tumor immunogenicity and effectively suppressing melanoma growth." (PMID 39174509, 2024). "Given the known role of IAP-SMAC deregulation in skin cancers and the lack of characterisation of LATS1-dependent apoptosis in melanoma we wanted to study the possible role of the novel LATS1-SMAC interaction in this cancer type." (PMID 35941108, 2022). "Deregulation of LATS1 and MST2 in melanoma is also relatively common in patients." (PMID 35941108, 2022).
melanoma (continued). "It is believed that activating MAPK mutations are critical for human melanocyte transformation; however, we found that murine melanocytes lacking Lats1/2 rapidly developed into melanomas without the initial presence of any other genetic alterations that stimulate the MAPK pathway." (PMID 35768444, 2022). "Analysis of Lats1/2−/− tumor sections revealed non-pigmented neoplasms which were remarkably similar to invasive BrafV600E/Lats1/2−/− mouse tumors, exhibited a comparable staining profile, and were subsequently diagnosed as mouse melanoma." (PMID 35768444, 2022). "Interestingly, LATS1 induced a significant increase in Caspase 3 activation in A375 melanoma cells (unlike the other two melanoma cell lines assayed) which was not enough to promote cell death." (PMID 35941108, 2022). "However, only in the case of melanocytes LATS1 silencing did not affect the proliferation of the melanoma cells in vitro, but it significantly increased tumor growth kinetics, and tumor weight after xenografting them into nude mice." (PMID 33803640, 2021). "To assess whether LATS1-mediated autophagy repression exerts a general function in various types of cancer therapy, we analyzed vemurafenib-mediated BRAF inhibition (BRAFi) in BRAFV600E-mutant A2058 melanoma cells." (PMID 31848340, 2019). "That leads us to conclude, that unlike in other models, LATS1 is not a primary kinase for YAP1 inactivating phosphorylation in melanocytes and melanoma." (PMID 33803640, 2021). "Thus, in melanoma rather than a restoration of sensitivity to PLX4032, proteasome inhibition and elevation of MST2 and LATS1 protein abundances seems sufficient for triggering apoptosis." (PMID 36038253, 2022).
cervical cancer (17 papers, 2009 to 2025). A primary or metastatic malignant neoplasm involving the cervix. "Although dysregulation of LATS1 and NF-κB has been associated with radioresistance in cervical cancer cells, research in this area is limited." (PMID 40699764, 2025). "A previous study found that LATS1 shows reduced expression in human cervical cancer and is associated with disease staging." (PMID 40699764, 2025). "Therefore, this study aimed to investigate the expression patterns of key Hippo pathway proteins (YAP, p-YAP, MST1, and LATS1) in cervical cancer and to evaluate their associations with clinicopathologic parameters." (PMID 41470136, 2025). "This study included participants diagnosed with advanced cervical cancer at stages IIIB and IVA, with a focus on analyzing the levels of LATS1 and NF-κB and their association with radiation therapy outcomes, as assessed according to the RECIST 1.1 criteria." (PMID 40699764, 2025). "In cervical cancer cell lines, LATS1 demonstrated an inhibitory effect on both the proliferation and invasion of cervical cancer cells, as predicted by the regulation of p27 and Matrix metalloproteinase-9 (MMP9)." (PMID 40699764, 2025). "The expression of miR-92a-3p is elevated in cervical cancer tissues and facilitates cell cycle progression in cervical cancer stem cells (CCSCs) by targeting LATS1." (PMID 40710326, 2025). "This study explored the roles of LATS1 and NF-κB as potential biomarkers for radioresistance in cervical cancer, specifically examining their relationship with radiation therapy response." (PMID 40699764, 2025). "This preliminary study aimed to investigate the effectiveness of LATS1 and NF-κB levels as a biomarker for radioresistance and evaluate their response to radiation in cervical cancer patients." (PMID 40699764, 2025). "The overexpression of LATS1 suppresses the proliferation of cervical cancer stem cells, leading to an increased percentage of cells in the G1 phase of the cell cycle and a reduced percentage of cells in the S phase." (PMID 40710326, 2025). "ROC analysis indicated that the area under the curve (AUC) for LATS1 was 32.7%, suggesting that LATS1 has an inverse predictive value as a candidate biomarker for radioresistance in patients with advanced cervical cancer." (PMID 40699764, 2025). "miRNAs − 21 is an essential miRNA that regulates the generation of radioresistance in HR-HPV-positive cervical cancer cells by inhibiting large tumor suppressor kinase 1 (LATS1)." (PMID 38965615, 2024). "A similar mechanism of resistance has also been proved in cervical cancer by targeting large tumor suppressor kinase 1 (LATS1)." (PMID 35309939, 2022). "AJUBA is an oncoprotein reported to negatively regulate the Hippo kinase LATS1, and the inhibition of LATS1 by AJUBA induces YAP activation in cervical cancer and CRC." (PMID 35885009, 2022). "The results showed that YAP1, the oncogenic effector of the Hippo pathway, was frequently (11%) amplified, while LATS1/2, MST1, and FATs, which are upstream tumor suppressors of the Hippo pathway, were frequently deleted or mutated in cervical cancer patients." (PMID 30840887, 2019). "Despite individual study having shown that miR-21 enhances radio-resistance of cervical cancer by targeting LATS1, we here filtered out 5 miRNAs (miR-16, miR-15a, miR-15b, miR-590 and miR-424), which possessed very high stringency with LATS1 gene 3’UTR." (PMID 28893265, 2017). "Evaluating the levels of LATS1 and NF-κB in patients with advanced cervical cancer receiving radiotherapy could provide valuable insights as prognostic markers." (PMID 40699764, 2025). "Therefore, an imbalance in the activities of LATS1/2 and NF-κB contributes to the increased radioresistance observed in cervical cancer cells undergoing radiation therapy." (PMID 40699764, 2025). "In advanced cervical cancer, LATS1 and NF-κB play similar roles in contributing to radioresistance." (PMID 40699764, 2025).
cervical cancer (continued). "High expression levels of TAZ and low expression levels of LATS1/2 could be an important factor in the poor prognosis of cervical cancer." (PMID 36552980, 2022). "Protein concentrations of Large Tumor Suppressor Kinase-1 (LATS1) and Nuclear Factor Kappa-B (NF-κB) have been identified as prospective biomarkers of radioresistance in cervical cancer." (PMID 40699764, 2025). "In turn, TGFα and AREG, via EGFR signaling, suppressed the Hippo pathway and activated YAP protein (dephosphorylated LATS1, MOB1, and YAP1) to promote cervical cancer cell growth." (PMID 30840887, 2019). "Secondly, both TGF-α and AREG dephosphorylate MOB1, LATS1, and YAP in cervical cells (Figs6 and 7), suggesting that the Hippo pathway is actively involved in the EGFR pathway regulation of cervical cancer progression." (PMID 26417066, 2015). "We mined TCGA cervical cancer datasets and found that besides YAP1 amplification, the upstream genes of the Hippo pathway, including MST1, LATS1/2, and FAT1/2/3/4, which negatively regulate YAP1 activity, were frequently deleted and/or mutated in cervical cancer patient samples." (PMID 30840887, 2019). "Intriguingly, AREG was able to suppress phosphorylation of LATS1, MOB1, and YAP in the cervical cancer cells, suggesting that AREG is not only a downstream target of the Hippo pathway, but also an important upstream regulator of the Hippo/YAP signaling pathway." (PMID 26417066, 2015). "Finally, knockdown of LATS1/2, the major suppressors of YAP, results in dephosphorylation of YAP in ME180 cervical cancer cells, leading to the significant increase in the cell proliferation and AREG secretion in both 2D and 3D culture systems." (PMID 26417066, 2015).
liver cancer (17 papers, 2015 to 2026). An epithelial or non-epithelial malignant neoplasm that arises from the liver. "In liver cancer, DNA methylation in the LATS1 promoter region leads to dysfunction of the Hippo signalling pathway, inducing excessive production of monoacylglycerol lipase and promoting malignant proliferation of liver cancer cells." (PMID 39937032, 2025). "Expression of a genetic variant of LATS1 (LATS1 rs7317471) in HCC patients exhibiting age below 53 years, female gender, smoking, alcohol drinking, and Barcelona clinic liver cancer stage B is associated with decreased risk of death." (PMID 36033517, 2022). "The expression of SMAD7 and LATS1/2 was down-regulated in liver cancer cells." (PMID 31711043, 2019). "The study reveals that TNFAIP8 promotes liver cancer growth through LATS1-YAP signaling." (PMID 30586922, 2018). "On the contrary, knockdown of Fascin-1 increased the phosphorylation of YAP and Lats1 and decreased the total and nuclear levels of YAP in Hep3B and HuH-6 cells, suggesting that Fascin-1 knockdown suppressed Hippo-YAP activation in liver cancer cells." (PMID 34897283, 2021). "For example, by inhibiting CUL4A-mediated LATS1 ubiquitination and increasing YAPS127 phosphorylation, lncRNA uc.134 can inhibit the progression of liver cancer." (PMID 34925511, 2021). "Overexpression of LATS1 and the nucleocytoplasmic translocation of YAP1 play an anti-oncogenetic role in the occurrence and development of liver cancer." (PMID 28076850, 2017). "Similarly, in QGY7703 and SMMC7721 liver cancer cells, NEDD4 acts as an oncoprotein, and overexpression of this protein was shown to suppress apoptosis via partially increasing large tumor suppressor kinase 1 (LATS1) expression." (PMID 36293239, 2022). "Similarly, in QGY7703 and SMMC7721 liver cancer cells, the overexpression of NEDD4 suppressed LATS1, which results in enhanced cell proliferation." (PMID 36293239, 2022). "In our study, we found that forced expression of Fascin-1 reduced the phosphorylation of YAP and Lats1 and increased the total and nuclear levels of YAP in HepG2 cells, indicating that Fascin-1 overexpression promoted Hippo-YAP activation in liver cancer cells." (PMID 34897283, 2021).